IL6ST (interleukin 6 cytokine family signal transducer)
Diseases named in the same sentence as IL6ST in open-access papers (continued):
Sharing a sentence is not in itself a finding about the gene and the disease.
Immunodeficiency (7 papers, 2017 to 2025). Failure of the immune system to protect the body adequately from infection, due to the absence or insufficiency of some component process or substance. "The latest IUIS classification has redefined DOCK8 deficiency as a combined immunodeficiency, and other genes like ZNF341 and components of the IL-6 pathway (IL6ST, IL6R) can cause HIES-like phenotypes." (PMID 41458089, 2025). "For DGKQ, IL6ST and ANKRD55, decreased expression correlated with reduced immune disease risk, and increased expression with higher risk." (PMID 41361473, 2025). "Here, we identify a patient with a causative homozygous mutation in IL6ST, encoding the human cytokine receptor subunit GP130, presenting with immunodeficiency and skeletal abnormalities including craniosynostosis, and demonstrate associated defects in IL-6, IL-11, IL-27, and OSM signaling." (PMID 28747427, 2017).
colon cancer (6 papers, 2011 to 2024). "Overall, we conclude that IL6ST may inhibit ferroptosis in colon cancer cells, providing a new combined target for enhancing the efficacy of ferroptosis inducers in the treatment of CRC." (PMID 39344518, 2024). "The present study demonstrated that IL6ST was highly expressed in colon cancer tissues and could inhibit ferroptosis." (PMID 39344518, 2024). "However, we found that low‐CD8‐expressing T cells showed higher IL6ST and ST2L expression in the colon cancer patients as well as endometrial cancer patients, confirming our findings on the CD8Low T lymphocytes upon cell starvation in vitro." (PMID 36504430, 2022).
depression (6 papers, 2020 to 2025). "We found multiple deregulated genes involved in pain, such as TNF, IL1B, and IL6ST, were identified as being associated with both depression and suicide." (PMID 40313396, 2025). "Subsequently, APOD, PON1, BCHE, and IL6ST were reported to be related to depression, a finding consistent with our results." (PMID 33126421, 2020). "IL-6 encodes a kind of cytokine, which plays a role in the process of inflammatory response and B-cell maturation by binding to receptors IL6R and IL6ST, whose dysregulation can precipitate multiple events relevant to depression, such as serotonin depletion and neurodegenerations." (PMID 39408591, 2024).
non-small cell lung carcinoma (6 papers, 2023 to 2025). A group of at least three distinct histological types of lung cancer, including non-small cell squamous cell carcinoma, adenocarcinoma, and large cell carcinoma. "It is noteworthy that the latest report has revealed that FXR promotes non-small-cell lung cancer metastasis by activating the Jak2/STAT3 signaling pathway through the transactivation of the IL6ST and IL6 genes." (PMID 39940889, 2025). "For instance, BAs activate the FXR receptor, thereby promoting the metastasis of non-small cell lung cancer (NSCLC) by mediating the JAK2/STAT3 signaling pathway through the transactivation of IL-6ST and IL-6 genes." (PMID 39769418, 2024). "In non-small cell lung cancer (NSCLC), FXR acts as a tumor-promoting driver, transactivating IL-6 and IL-6ST and activating the Jak2/signal transducer and activator of transcription 3 (STAT3) pathway, thereby enhancing metastatic potential and poor prognosis." (PMID 41339918, 2025). "In addition, the IL6ST targeted drug siltuximab is undergoing I/II trials for solid tumors, while the EPHB4-targeted drug tesevatinib is undergoing I/II trials for solid tumors and non small cell lung cancer." (PMID 41261599, 2025).
Obesity (6 papers, 2018 to 2026). Accumulation of substantial excess body fat. "In obesity, increased AT IL6, IL6R, and SOCS3 mRNA expression was observed, however, unchanged AT IL6, IL6R and IL6ST expression was also reported." (PMID 29737494, 2018). "First, we identified gene sets related to the function of each obesity-related serum factor: HG/HI (Insr, Irs1, Rps6kb1, Slc2a4, Slc2a5, Slc2a1), TNF-α (Tnfrsf1a, Tradd, Traf2, Fadd), IL-6 (Il6ra, Il6st, Jak1), and fatty acids (PA, LA, Chol; Ffar1, Ffar4, Ppara, Pdk4, Pgc1a)." (PMID 37047207, 2023). "Due to high species conservation, the identified genes related to human or mice obesity traits may hold importance for adipose deposition in chickens, such as ELOVL7, IL6ST, IQGAP2, PAX5 and CKMT2." (PMID 34058970, 2021).
colorectal cancer (5 papers, 2017 to 2025). A primary or metastatic malignant neoplasm that affects the colon or rectum. "Fourth, this study investigated the correlation between IL6ST and ferroptosis without in-depth mechanistic studies, and we hope that in-depth mechanistic studies will be conducted in the future, which will provide a direction for the development of new drugs for the treatment of colorectal cancer." (PMID 39344518, 2024).
hepatocellular carcinoma (5 papers, 2016 to 2025). A malignant tumor that arises from hepatocytes. "Additionally, studies have shown miR‐224‐5p is associated with IL6ST expression in hepatocellular carcinoma, suggesting a potential diagnostic role, though the mechanism is not well defined." (PMID 39840666, 2025). "Here, we demonstrate that YAP1 and IL6ST are novel substrates of chaperone-mediated autophagy (CMA) in human hepatocellular carcinoma (HCC) and hepatocyte cell lines." (PMID 35435804, 2023).
inflammatory bowel disease (5 papers, 2018 to 2025). A spectrum of small and large bowel inflammatory diseases of unknown etiology. "Therefore, is blocking IL6ST a promising approach for treating inflammatory bowel disease or even other inflammatory diseases in the future?" (PMID 39007267, 2024). "Hence, our study confirmed that screening suitable inhibitors of IL6ST with few side effects may be a promising approach for treating inflammatory bowel diseases in the future." (PMID 39007267, 2024).
metabolic syndrome (5 papers, 2013 to 2023). A cluster of metabolic risk factors for CARDIOVASCULAR DISEASES and TYPE 2 DIABETES MELLITUS. "Finally, it is important to notice that this and other variants in the IL6ST gene have been associated with increased prevalence of metabolic syndrome and higher BMI." (PMID 28250574, 2017).
prostate carcinoma (5 papers, 2012 to 2025). A carcinoma that arises from epithelial cells of the prostate gland. "The prostate cancer cell line LNCaP, used as an IL6R positive control, had similar expression levels of IL6R and IL6ST compared to ES cell lines." (PMID 26215971, 2015).
Stüve-Wiedemann syndrome (5 papers, 2023 to 2025). "Patients with homozygous amorphic mutations in IL6ST or LIF receptor (LIFR) develop Stüve-Wiedemann syndrome." (PMID 40526438, 2025). "In a heterozygous setting, these variants do not cause a phenotype, but in homozygous setting such variants are pathogenic and cause a Stüve-Wiedemann syndrome phenotype (intronic splice site variant within the IL6ST locus, c.1699+4A>G)." (PMID 38133879, 2023). "It is likely to have a similar role in patients with loss-of -function IL6ST variants that are limited to the hematopoietic system, but this will not be effective in treating the multi-organ manifestations of severe Stüve-Wiedemann syndrome." (PMID 38133879, 2023). "Interestingly, biallelic LoF mutations in IL6ST, the gene encoding gp130, are associated with extended Stüve-Wiedemann syndrome (OMIM:600694)." (PMID 39847438, 2025). "The TRPS1 and IL6ST genes are associated with trichorhinophalangeal syndrome (OMIM #190350) and Stuve-Wiedemann syndrome (OMIM #619751) in autosomal dominant and recessive modes, respectively." (PMID 39989454, 2025).
breast neoplasm (4 papers, 2021 to 2024). A benign or malignant neoplasm of the breast parenchyma. "Further work is needed to determine the role of these or other gp130/IL6ST aberrations in other epithelial cancers, including breast neoplasms." (PMID 34834425, 2021). "IL6ST has been shown to play important roles in homeostasis, immunity, inflammation, and disease pathogenesis, having an established part in numerous cancer types, such as breast neoplasms, and such roles are involved in many hallmarks of cancer development and progression." (PMID 39201290, 2024). "However, IL1R1, ILRAP, IL6ST, CXCL3, CXCL5, and CXCL6 gene expression was higher in normal adjacent tissue than in breast tumor tissue." (PMID 39201290, 2024). "However, IL1R1, ILRAP, IL6ST, CXCL3, CXCL5, and CXCL6 gene expression levels were higher in normal adjacent tissue than in breast tumor tissue indicating that the surrounding non-tumor tissue could also present an inflammation." (PMID 39201290, 2024).
colitis (4 papers, 2011 to 2026). Inflammation of the colon. "The reduction in the capacity of the IL-6ST/gp130 receptor to activate STAT1 and STAT3 in our heterozygous GP130∆STAT/+ mice demonstrates that IL-6ST/gp130 receptor signalling is required for the maintenance of intestinal barrier function during colitis." (PMID 33673239, 2021). "Together, these findings demonstrate that IL-6ST/gp130/STAT3 activation plays a prominent role in regulating intestinal barrier function during colitis." (PMID 33673239, 2021). "To investigate the functional role of IL-6ST/gp130-dependent STAT3 during colitis development, we induced acute colonic injury and inflammation by administration of DSS via drinking water." (PMID 33673239, 2021). "Similarly, in colon tissue from a human with active colitis, EPICERTIN significantly upregulated CSF2 and tissue repair-associated genes while downregulating proinflammatory genes (IL1B, IL6ST)." (PMID 41651223, 2026). "However, the significance as well as the cellular mechanisms by which IL-6ST/gp130/STAT3 signalling promote barrier integrity during DSS-induced colitis are yet to be elucidated." (PMID 33673239, 2021). "Thus, the profound induction of Reg3b and Reg3g in GP130ΔSTAT/+ mice strongly implicates that IL-6ST/gp130/STAT3 signalling contributes to the regulation of host microbiome composition during colitis." (PMID 33673239, 2021). "Our data indicate that IL-6-mediated IL-6ST/gp130 signalling drives STAT3 activation, by which STAT3 modulates intestinal permeability through the expression of tight junction proteins during the development of colitis." (PMID 33673239, 2021).
lung carcinoma (4 papers, 2017 to 2025). "The activation of the IL6/IL6ST/JAK/STAT3 pathway contributes significantly to lung cancer development, including tumor growth, angiogenesis, and malignant progression." (PMID 39840666, 2025). "In lung cancer, silencing of NFIX induced a decrease in IL6ST, TIMP1, and ITGB1 gene expression and reduced cell proliferation, migration, and invasion processes." (PMID 31766658, 2019). "Hence, NFIX with IL6ST, TIMP1, ITGB1, PTCH1, GGCX and NFAT5 genes may regulate the migration and invasion process and they could serve as potential therapeutic targets in patients with lung cancer to predict survival and improve prognosis." (PMID 28871224, 2017).
multiple sclerosis (4 papers, 2021 to 2025). A progressive autoimmune disorder affecting the central nervous system resulting in demyelination. "A previous study identified rs7731626 as likely causal for multiple sclerosis and RA and was also a T cell-specific eQTL for both IL6ST and ANKRD55." (PMID 37289818, 2023).
ovarian carcinoma (4 papers, 2020 to 2024). A malignant neoplasm originating from the surface ovarian epithelium. "IL10, IL6, IL6ST, and macrophage scavenger receptor 1 (MSR1; CD204) were positively correlated with ovarian cancer patients in the high-risk group using heatmap analyses of the signature with the immune-related genes." (PMID 33381581, 2020). "Notably, we found that OSMR, LIFR, IL6R, and IL6ST mRNA were highly upregulated in cisplatin-resistant ovarian cancer cells in both A2780 and OVCAR8 cells." (PMID 38839865, 2024). "In consistent with mRNA data, protein levels of OSMR and its dimerizing partner IL6ST are highly upregulated in cisplatin-resistant A2780, OVCAR8, PEO4 and MCW-OV-SL3 ovarian cancer cell lines compared to their respective controls." (PMID 38839865, 2024). "Another strategy involves the direct targeting of gp130/IL6ST with small-molecule inhibitors such as SC144, which has shown promise in preclinical ovarian cancer models." (PMID 34834425, 2021). "Given that the receptors and ligands that activate the autocrine signaling through OSMR are highly expressed in cisplatin-resistant ovarian cancer cells, we sought to determine the level of OSMR/IL6ST heterodimerization in the cisplatin resistant cells compared to the sensitive cells." (PMID 38839865, 2024).
renal fibrosis (4 papers, 2021 to 2025). A final common manifestation of a wide variety of chronic kidney diseases characterized by glomerulosclerosis and tubulointerstitial fibrosis. "IL6ST upregulation abolished si-circ_0008925-mediated the inhibition on TGF-β1-induced HK-2 cell injury and fibrosis, verifying that circ_0008925 promoted renal fibrosis by positively regulating IL6ST level." (PMID 40038566, 2025). "Our results suggested that IL-6 affects renal fibrosis by acting on IL6ST in DN progression, and the IL6ST/STAT3/NF-kB signaling pathway plays an important role in DN progression." (PMID 33995063, 2021). "In addition, IL6ST expression was decreased by curcumin, and its overexpression also overturned the function of curcumin on renal fibrosis, confirming the conclusion of curcumin regulated circ_0008925/miR-204-5p/IL6ST axis in renal fibrosis." (PMID 40038566, 2025). "Curcumin relieved renal fibrosis through regulating circ_0008925/miR-204-5p/IL6ST axis." (PMID 40038566, 2025). "Above all, we pointed out that curcumin might inhibit renal fibrosis through the circ_0008925/miR-204-5p/IL6ST axis." (PMID 40038566, 2025). "Moreover, the authors suggested that Malat1upregulation is able to increase renal fibrosis in diabetic rats and damageHG-incubated HK-2 cells by acting through the miR-2355-3p/IL6ST pathway." (PMID 37272835, 2023). "In conclusion, these findings demonstrated that lncRNA MALAT1 might enhance renal fibrosis in diabetic rats and cell damage in HG-induced HK-2 cells via the miR-2355-3p/IL6ST axis." (PMID 33995063, 2021). "In conclusion, MALAT1 overexpression may enhance renal fibrosis in diabetic rats and cell damage in HG-induced HK-2 cells via the miR-2355-3p/IL6ST axis, which provides a new perspective of DN treatment." (PMID 33995063, 2021).
Stroke (4 papers, 2014 to 2021). Sudden impairment of blood flow to a part of the brain due to occlusion or rupture of an artery to the brain. "Post-stroke angiogenesis resembles in many ways the angiogenesis in tumors, i.e., the newly formed vessels are leaky via the Il6r/Il6st/STAT1/3 pathway." (PMID 24672479, 2014). "However, DRD2 and C5aR1 are absent or negligible in marmoset reactive astrocytes with only ESR1 & IL6ST significantly upregulated 1-week after stroke." (PMID 34824275, 2021). "An increased expression of the newly identified stroke genes Il6ra, Il6st, S100a4, Stat1, and Stat2, but also the known genes Col1a1, Col1a2, Col3a1, has been implicated in blood vessel remodeling and contributes to vascular rarefaction, leakage, and intracranial aneurysms." (PMID 24672479, 2014).
viral infection (4 papers, 2019 to 2024). "Interestingly, we observed in mouse PCLS no induction of Il6r or Il6st gene expression upon virus infection, but BRO upregulated both Il6r and Il6st, as well as Adam17 in the presence but also in the absence of virus." (PMID 31067687, 2019).
Autoimmunity (3 papers, 2022 to 2025). The occurrence of an immune reaction against the organism's own cells or tissues. "While, IL-6 trans-signalling and trans-presentation may be a more potent inducer of autoimmunity than classic signalling, our finding that blood IL6R and IL6ST expression are associated with increased risk of type 1 diabetes may be explained by any of the three signalling modalities." (PMID 39271518, 2024).
diabetic nephropathy (3 papers, 2021 to 2025). "In diabetic nephropathy, miR-223 is downregulated, and miR-223-3p has been shown to mediate the diabetic kidney disease progression by targeting IL6ST/STAT3 pathway, indicating protective mechanisms against diabetic kidney disease." (PMID 41295241, 2025). "Research on molecular mechanism illustrated long noncoding RNA metastasis-associated lung adenocarcinoma transcript 1 (lncRNA MALAT1) mediated diabetic nephropathy by sponging miR-2355-3p/IL6ST axis." (PMID 35611768, 2022).
endometriosis (3 papers, 2020 to 2025). The growth of functional endometrial tissue in anatomic sites outside the uterine body. "Persistent activation of STAT3 by IL6ST signaling has been associated with development of fibrosis in endometriosis." (PMID 39821173, 2025). "Level of methylation of IL6ST is diminished in patients with endometriosis, whereas level of mRNA expression is markedly elevated by RT-PCR." (PMID 39821173, 2025). "Despite numerous reports on epigenetic modifications in endometriosis, there is relatively limited research specifically addressing the methylation of IL6ST molecule." (PMID 39821173, 2025). "Furthermore, IL6ST facilitated progression of endometriosis by activating mitogen-activated protein kinase 9/Signal Transducer and Activator of Transcription 3 signaling pathway." (PMID 39821173, 2025). "Comparative analysis of clinical ovarian endometrial tissue with normal uterine tissue using RT-PCR revealed significant differential methylation in promoter region of IL6ST, indicating markedly increased IL6ST expression and heightened methylation status in endometriosis." (PMID 39821173, 2025). "Given that changes in IL6ST methylation status influence progression of various diseases, coupled with our laboratory’s previous sequencing results, we aim to validate the role of IL6ST in endometriosis and its related pathways." (PMID 39821173, 2025). "Moreover, it is plausible that IL6ST is activated prior to the commencement of aberrant endometrial growth and proliferation, with its expression intensifying during the malignant transformation of endometriosis." (PMID 39821173, 2025). "Upregulation of IL1RL1, IL6ST, TNFRSF1B, and NR3C1 has been described in women with endometriosis." (PMID 38069001, 2023).
myeloma (3 papers, 2007 to 2022). "In addition, IL6ST variants were significantly enriched in RRMM compared to NDMM (P < 0.001, one-sided Fisher’s exact test), which reflects the progressive independence of the myeloma cells from bone marrow cytokines in some advanced patients." (PMID 35768438, 2022).
Sepsis (3 papers, 2021 to 2024). Sepsis is defined as life-threatening organ dysfunction caused by a dysregulated host response to infection. "Notably, the analysis of mouse models of LPS-induced sepsis showed that the increased protein expression of IL6ST and WTAP was reduced in the lung and colon tissues from LyzM-Cre+WtapΔ1–77 mice." (PMID 39007267, 2024).
steatosis (3 papers, 2014 to 2021). Increased lipid within the cytoplasm of cells. "Alteration in CCR7, IMPDH2, IL6ST, MYC, LPIN1, PDE7A and RORA was significantly associated with hepatotoxicity including liver damage, -hyperplasia, -inflammation, -steatosis, -fibrosis, -necrosis and -proliferation." (PMID 26907258, 2016). "Global deletion of IL-6 signal transducer (Il6st; also called gp130) produces a similar liver phenotype, characterized by steatosis, inflammation, and fibrosis." (PMID 24802098, 2014).